VEGFA (vascular endothelial growth factor A)
Diseases named in the same sentence as VEGFA in open-access papers (continued):
Sharing a sentence is not in itself a finding about the gene and the disease.
tumor (continued). "TAM-M2s secrete various pro-angiogenic factors including vascular endothelial growth factor-A (VEGF-A), TNFα and produces different factors responsible for the induction of lymphangiogenesis, thereby supporting tumor cell proliferation, angiogenesis, invasion, and cancer stem cell functions." (PMID 33522932, 2021). "In addition, the S1PR1 antagonist BAF312 effectively inhibited tumor growth and decreased angiogenesis by affecting S1PR1/P-STAT3/VEGFA signaling." (PMID 34059068, 2021). "Among tumor-derived angiogenic factors and cytokines, vascular endothelial growth factor A (VEGF-A, also called VEGF) is the major mediator of tumor angiogenesis, specifically the two circulating isoforms-VEGF121 and VEGF165 signaling through VEGF receptor 2 (VEGFR-2)." (PMID 34686154, 2021). "In addition, m6A modification can also regulate the expression of VEGFA through the miR-143-3P/VASH1 axis, as well as through the regulation of SERPINE2, IL11, and HDGF stability, thus affecting tumor angiogenesis." (PMID 33926508, 2021). "Notably, IBI188 treatment increased vascular endothelial growth factor-A (VEGF-A) levels in a solid tumor model, and combined treatment with an anti-VEGF-A antibody and IBI188 resulted in an enhanced anti-tumor effect." (PMID 34717705, 2021). "Overall, our data suggests that targeting MYCN may limit tumor cell migration in RB possibly via downregulating the expression of ECM proteins and VEGFA." (PMID 34680394, 2021). "In vitro and in vivo studies both confirm that BAF312@cRGD-CaP-NPs showed dramatically improved tumor targeting ability and can effectively improve the antitumor effect of BAF312 and inhibit tumor angiogenesis, which is mediated through the S1PR1/P-STAT3/VEGFA pathway." (PMID 34059068, 2021). "Finally, we explored the possible regulatory mechanism of PVT1 and observed that miR-152-3p, a tumor suppressor, contains binding sites at the 3′-UTR of PVT1 and VEGFA." (PMID 34336125, 2021). "Compared to monotherapy, in the bearing-tumor mice without high expression of VEGFA, combination treatment showed no synergistic effect in antitumor efficacy." (PMID 34497663, 2021). "VEGFA is highly elevated in ascites from human EOC patients, upregulated by lysophosphatidic acid, an oncolipid in EOC, and functionally involved in angiogenesis, tumor growth, metastasis, drug resistance, and vascular permeability." (PMID 34359722, 2021). "Notably, earlier drug studies in RT2 mice targeting c-Myc, VEGFA, and PI3K/Akt/mTOR signaling, yielded similar phenotypes of reduced tumor progression and angiogenesis as seen in RT2; R6KO animals." (PMID 34199469, 2021). "FGF2 upregulates VEGFA expression in various types of cells, including HCC tumor cells." (PMID 33802841, 2021). "The increased tumor growth after bevacizumab treatment could be also related to the induction of HIF-1α and VEGFA, observed when UM cells were exposed in vitro to hypoxia and treated with bevacizumab, thus inducing “pseudohypoxia” as defined by the authors." (PMID 33964953, 2021). "The primary data indicated that compare with wild-type cells, overexpressed miR-26a significantly lost it tumor suppressive effects in the absence of VEGFA (data not shown)." (PMID 35201478, 2021). "VEGFA belongs to the VEGF family and is an important factor in the promotion of tumor angiogenesis." (PMID 34194533, 2021). "Vascular endothelial growth factor A (VEGF-A) is considered to be a critical regulator of angiogenesis, which is the formation of new blood vessels from pre-existing ones, both in physiological and pathological states such as tumor angiogenesis." (PMID 33854498, 2021). "Tumor internal environment can induce HIF-1 activating cells, to release a large amount of vascular endothelial growth factor-A (VEGF-A), vascular endothelial growth factor-2 (VEGF-2), fibroblast growth factor-2, and stromal cell-derived factor-1α/β (SDF-1α/β)." (PMID 34616746, 2021).
tumor (continued). "Hypoxia is a key driver of tumour angiogenesis and hypoxic cancer cells secrete vascular endothelial growth factor A (VEGFA), which initiates tumour angiogenesis binding to VEGF receptor 2 (VEGFR2) expressed on the endothelial cells of neighbouring blood vessels." (PMID 33544155, 2021). "For example, VEGFA induces the expression of transcription factor TOX to drive T cell exhaustion, and the expression of CASP1 is able to be repressed by G9A and further promotes tumor immune escape." (PMID 34394098, 2021). "Nonetheless, the expression of inhibitory and suppressive markers, including genes for IL-4R, IL-10, IL-6, VEGFA, CCL2 and IL-1β, were mostly expressed by cluster 0, suggesting that these cells had a tumor-promoting and immune-suppressing functions, which resemble MDSC-like cells." (PMID 34025646, 2021). "Vascular endothelial growth factor-A (VEGFA) exerts a major influence on junction leakiness and, given its high level of production in tumors, there will be an increased propensity towards tumor vascular leakiness, facilitating the metastatic process." (PMID 34768912, 2021). "After leaving the primary site, tumor cells are attracted to blood vessels where they interact with perivascular TIE2+ macrophages, which increases vessel permeability and promotes tumor cell escape in part by secreting VEGFA." (PMID 34178692, 2021). "Tumor-secreted GM-CSF, CXCL12, and CCL2 attract monocytes to the TME and drive their differentiation into M2 TAMs, which then promote angiogenesis through secretion of Matrix Metalloproteinase 9 (MMP9) and Vascular Endothelial Growth Factor A (VEGF-A)." (PMID 34830776, 2021). "M2 macrophages secrete pro-tumorigenic, pro-angiogenic, and immunosuppressive factors such as IL10, TGFβ, and VEGFA; whereas M1 macrophages produce pro-inflammatory cytokines such as TNFα, IL1, IL12, and IFNγ, and reactive oxygen species, which prevent tumor growth." (PMID 34517894, 2021). "However, the correlation of KLF4 mRNA levels with the mRNA levels of VEGFA, SLC2A3 and HK2 was only moderate to weak in the analyzed tumor samples (R = 0.5044; R = 0.3348; R = 0.4416)." (PMID 32245394, 2020). "Additionally, flow stasis in impaired tumor vessels promotes hypoxia, which upregulates angiogenic molecules such as vascular endothelial growth factor-A (VEGF-A, referred to as VEGF), further promoting tumor growth." (PMID 33217955, 2020). "The results obtained from surgical solid biopsy support the idea that some GBM patients have a tumor with a high angiogenic phenotype (patients 8 and 2), while in others, VEGFA protein expression is absent (patient 11)." (PMID 32564774, 2020). "HIF1α is considered the fundamental initiator of tumor angiogenesis, which initiates the process through regulating the key angiogenic factor vascular endothelial growth factor A (VEGFA) via a hypoxia-response element (HRE) present in the VEGFA promotor." (PMID 32545251, 2020). "Several studies have demonstrated that the hypoxia inducible factor-1alpha (HIF-1α) stabilization, favored by the hypoxic MM BM niche, induces the transcription of a few pro-angiogenic factors, including Vascular Endothelial Growth Factor A (VEGF-A), both in tumor and stromal cells." (PMID 33489901, 2020). "The findings also indicate that miR-1224-5p inhibits cell proliferation, colony formation, migration and invasion in vitro and tumour growth in vivo by targeting TNS4, and subsequently promoting the autophagic degradation of EGFR, and suppressing downstream EFNA1/EPHA2 and VEGFA signalling pathways." (PMID 32732965, 2020). "The resulting tumor interactome network highlighted several recurring modules, including a large matrix remodeling module, modules centered around ERBB, HGF‐MET, TGFbeta, FGF, IGF, and VEGFA, a lipid trafficking module, and a WNT planar cell polarity module." (PMID 33332768, 2020).
tumor (continued). "Our study adds to these findings by demonstrating that the interaction between the adipocytes and macrophages in the absence of tumor cells is sufficient to promote a pro-angiogenic phenotype in the macrophages, particularly the expression of VEGFA." (PMID 32318345, 2020). "We found that target molecules of these inhibitors, including VEGFR1, VEGFR2, VEGFR3, VEGFA and PDGFRB, were markedly expressed only in cancer 1 and 2 clusters (primary tumor and LN metastasis), while their expressions in cancer 4 (bone metastasis) and CSC clusters were relatively low." (PMID 33162821, 2020). "Moreover, high CD74 co-expression with immunosuppressive genes VEGFA and HIF1α and hematopoietic marker CD45 and tumor marker MultiKRT demonstrates that CD74 is expressed by both the tumor cells and the immune cells." (PMID 33228231, 2020). "For example in tumor P22 (basal), three focal amplicons encompassing the VEGFA, MYC and CCNE1 loci were found in varying proportions and in certain instances (VEGFA and CCNE1) in a mutually exclusive manner in sequenced single-nuclei (p-value=0.003 – Fisher’s Exact Test)." (PMID 32401198, 2020). "Moreover, we examined the expressions of miR-195-5p and VEGFA in the tumor tissues of the xenograft mice, and the results showed that shDXL6-AS1 significantly promoted the miR-195-5p expression and suppressed the VEGFA expression compared with the shNC group." (PMID 32756011, 2020). "Recent studies have shown that hsa-miR-130b-3p acts as a tumor suppressor, inhibiting cancer angiogenesis by specifically targeting tumor necrosis factor-α (TNF-α), thereby suppressing the nuclear factor-κB/vascular endothelial growth factor-A (NF-κB/VEGFA) signaling pathway." (PMID 32423052, 2020). "There was a negative correlation in the tumor tissue between miR-612 and VEGFA expression, and between miR-612 and miR-17-5p and NFE2L2 expression." (PMID 32824922, 2020). "Analysis conducted on SQC patients also showed no statistical difference between the protein expression of VEGFA and the different lymph node status as well as tumor grade." (PMID 31892982, 2020). "In a recent clinical trial of EZN-2968, the antisense oligonucleotide inhibitor of HIF-1α successfully down-regulated both mRNA and protein levels of HIF-1α but failed to reduce the expression of VEGFA in tumor biopsies." (PMID 33351793, 2020). "There was a statistically significant difference in the immunoexpression of HIF-1α, MMP-2, VEGF/VEGFA, and VEGFR-2 proteins between the parenchyma of tumour cells and the stroma of tumour cells, where the parenchyma cells of AME showed a higher immunoexpression compared to the stromal cells." (PMID 33067558, 2020). "Tumor cells further express NGF, which has similar angiogenic effects as VEGFA." (PMID 33324652, 2020). "The data suggest that there are more than 20% of GBM patients whose tumor growth is independent of the VEGFA pathway, so they would not benefit from an anti-angiogenic treatment." (PMID 32564774, 2020). "Identification of the possible roles of miR-17-5p and miR-612 in the regulation of NFE2L2 and VEGFA expression in PTC and colloid goiter can provide valuable insights for the development of strategies and drugs to inhibit tumor growth and also to restore sensitivity of tumors to chemotherapy." (PMID 32824922, 2020). "Moreover, immunohistochemical staining showed a marked decrease in HIF-1α, VEGFA, and CD31 expression in 20(S)-Rg3 group tumor tissues." (PMID 32382013, 2020). "With the regulation of the tumor microenvironment, more genes were upregulated with over two-fold differences in both HK1 and C17 xenografts after CYLD knockout, including BCL2A1, CXCL1, BIRC3, SERPINB2, total VEGF, TNFA, and VEGFA." (PMID 32708712, 2020).
tumor (continued). "Macrophages are recruited at TME, in response to the secretion by tumor cells and other TME cell types, of a number of chemoattractant soluble factors, including vascular-endothelial growth factor A (VEGF-A), chemokine ligand 2 (CCL2), and colony-stimulating factor 1 (CSF-1)." (PMID 32878276, 2020). "We further found that vascular endothelial growth factor A (VEGFA), part of the PDGF/VEGF growth factor family and key factors in tumor vessel formation, is a miR-106a-5p target at the 3′-UTR of the VEGFA mRNA and miR-106a-5p contributes to a decrease in VEGFA." (PMID 33224312, 2020). "In contrast, we and others have shown that VEGFA plasma values do not represent the real angiogenic tumor status." (PMID 32564774, 2020). "Moreover, in a research on triple‐negative breast cancer (TNBC), heparin‐binding epidermal growth factor (HB‐EGF) was found to play a pivotal role in the acquisition of tumor aggressiveness by regulating both ANGPTL4 and VEGFA." (PMID 32410376, 2020). "Both VEGFA and NGF promote MMP production facilitating tumor invasion and cancer angiogenesis." (PMID 33324652, 2020). "The importance of the NOTCH1/HES1/DLL4/VEGFA/MMP13 axis in cholangiocarcinogenesis was confirmed in a collection of human iCCA tumor patients, paving the path for further investigations into the role of these genes in this tumor type." (PMID 32042099, 2020). "We also analyzed the relationship between VEGFA protein level and TNM stage, tumor size in SQC." (PMID 31892982, 2020). "VEGFA contributed to OSCC cell proliferation and tumor initiation." (PMID 33330021, 2020). "LN3s express higher levels of macrophage-inhibitory cytokine-1 (MIC1/GDF15), the chaperone gp96 and VEGFA, and have greater tumor vascularity than non-metastatic LNCaP lines." (PMID 31006104, 2019). "Vascular endothelial growth factor-A (VEGF-A), is a key angiogenic factor that has multiple functions, including vasculogenesis, inflammation, and vascular permeability, which are important in tumor angiogenesis." (PMID 31448053, 2019). "Curative treatment with BMS309403 significantly decreased tumor FABP4 (p = 0.04), cyclin D1 (p = 0.02), VEGFA (p = 0.002) and VEGFR (p = 0.001) expression compared to the control group, while active caspase 3 was induced (p = 0.008) in parallel with mTOR pathway downregulation." (PMID 30575815, 2019). "The study also highlighted the inefficacy of anti-VEGFA therapy in this type of tumor, unlike what observed in other type of cancers." (PMID 31263680, 2019). "NK cells might act as inhibitors of vascular endothelial growth factor-A (VEGF-A) expression by neutrophils via an IFN-γ-stimulated pathway that promotes angiogenesis and, consequently, tumor growth." (PMID 30944838, 2019). "It is noteworthy that expression levels of VegfA and Hif1a are higher in metastatic lymph nodes of WT and Stat4−/− mice compared to primary tumors and non-metastatic lymph nodes of tumor bearing mice." (PMID 32010142, 2019). "About this issue, the traditional view is that VEGFA high expression will lead to vascular abnormalities, further aggravation of hypoxia and the activation of HIF-1a pathway in tumor tissues, which could result in increased expression of PD-L1 on tumor cells." (PMID 30972298, 2019). "Collectively, our results suggested that downregulation of VEGFA expression by increased MIR452 levels in CRC tissues and cells might act as an early inhibitory mechanism against tumor progression in CRC tissues." (PMID 31652600, 2019). "Therefore, we visualized VEGFA and CD31 levels of tumor xenografts in nude mice by immunohistochemistry (IHC) staining; CD31 levels are indicative of microvessel density (MVD)." (PMID 30367150, 2019). "It is hard to conclude that VEGFA/76336/ES promotes tumor growth due to a lack of experimental evidence." (PMID 31552163, 2019). "Gene expression of VEGFA was significantly increased (P < 0.0368) in tumor stromal cells maintained in 3DH environment, but not greatly affected upon hMSC transfer to 3DH." (PMID 30862796, 2019).
tumor (continued). "Also, in tumor tissues, depletion of Bclaf1 considerably suppressed the expression of HIF1A, explaining the decrease of VEGFA protein levels." (PMID 30367150, 2019). "IHC was used to evaluate VEGFA, CD34 and proliferation marker Ki67 in tumor tissues." (PMID 30755242, 2019). "In NPC tumor tissues, HOTAIR overexpression promotes angiogenesis and tumor growth by directly activating the transcription of vascular endothelial growth factor-A (VEGF-A) and glucose-regulated protein 78 (GRP78) as well as through GRP78-mediated upregulation of VEGFA and Ang2 expression." (PMID 31336999, 2019). "Additionally, over-expression of VEGFA has been confirmed in a majority of patients with NSCLC, some studies reported that there was a positive correlation between tumor vascularization and poor disease-free survival (DFS) or overall survival (OS)." (PMID 30972298, 2019). "miRNA-1 and miRNA-206 were demonstrated to target vascular endothelial growth factor A (VEGFA) and chemokine (C-C motif) ligand 2 (CCL2), while miRNA-31 was found to target forkhead box O3 (FOXO3a, a tumour suppressor) that was suggested to inhibit VEGFA expression in fibroblasts." (PMID 30944831, 2019). "The promotive role of VEGFA in EMT process has also been unveiled in a recent study, which suggested that VEGFA could elevate the tumor-initiating stem cell population in different cancers, and also induce EMT and metastasis." (PMID 31719795, 2019). "However, Xu et al33 found that short‐term anti‐VEGFA treatment induced increase VM and metastasis in SKOV3LUC+ tumour‐bearing mice." (PMID 30945361, 2019). "Indeed, VEGFA drives the recruitment of VEGFR2-expressing Treg and decreases T cell extravasation at the tumor–endothelium interface." (PMID 31892230, 2019). "However, in the CGC tumour tissues, the genes most frequently showing CNGs were CDKN1B (42.9%), H3F3A (23.8%), CDK2 (14.3%), NFKBIA (14.3%), and VEGFA (14.3%)." (PMID 30989433, 2019). "Some of the genes involved include VEGFA (angiogenesis), WNT1 (proliferation), ERBB3 (proliferation), SMAD4 (tumor suppressor), NDRG2 (radioresistance) and EGFR (invasiveness) all leading to tumor aggressiveness." (PMID 30842790, 2019). "First, MDSCs induce angiogenesis via secreting VEGFA and MMP-9, which in turn promote tumor growth." (PMID 29541408, 2018). "Based on these results, we conclude that miR-150-5p may function as a tumor suppressor in CRC, and miR-150-5p/VEGFA axis may be a potential therapeutic target candidate in CRC treatment." (PMID 30476901, 2018). "Once confined to the tumor vasculature, myeloid cell secretion of pro-angiogenic factors and matrix-degrading enzymes both induces EC proliferation and also degrades the ECM, which makes way for sprouting vessels and releases VEGFA." (PMID 30158456, 2018). "When macrophages were ablated with clodronate, the level of graft vascularisation remained unchanged, suggesting that macrophages are not required for angiogenesis in tumour xenografts with low levels of VEGFA." (PMID 30396905, 2018). "The high expression of both factors was also associated with increased IL-8 expression in GBM tissues, but in vitro stimulation with Ang-2 and/or VEGFA did not indicate tumor or endothelial cell-specific IL-8 responses." (PMID 29644004, 2018). "A2V, a novel bevacizumab-based bispecific human IgG1 antibody that targets Ang2 and VEGFA, has been found to promote anti-tumor immunity by activating tumor-infiltrating CD8+ T cells, increasing tumor antigen presentation, and enhancing perivascular T-cell accumulation." (PMID 29560266, 2018). "There was no observed significant correlation between dichotomized tumor PD-L1 expression (positive/negative) and VEGFA (P = 0.41), VEGFR1 (P = 0.65), and VEGFR2 (P = 0.73)." (PMID 29623256, 2018). "Indeed studies have shown that the use of bevacizumab, or of other VEGFA/VEGFR2-targeting drugs, has been followed by adaptive tumour responses in preclinical models and clinical settings." (PMID 29721204, 2018).